INS (insulin)
Diseases named in the same sentence as INS in open-access papers (continued):
Sharing a sentence is not in itself a finding about the gene and the disease.
Insulin resistance (continued). "The elevated systemic FFAs had a role in increased very low density lipoprotein production and inhibition of insulin clearance that lead to insulin resistance." (PMID 31289463, 2019). "In the liver, insulin resistance leads to chronic damage and fibrosis, but it is unclear how tissue-repair mechanisms integrate insulin signals to coordinate an appropriate injury response or how they are affected by insulin resistance." (PMID 30695023, 2019). "In study conducted in patients with insulin resistance, irisin levels were determined to increase with the insulin resistance and decrease as insulin sensitivity increases." (PMID 31881940, 2019). "Some studies reported positive correlations between total serum calcium with insulin level and insulin resistance and fasting serum glucose in the larger healthy population." (PMID 31814932, 2019). "High-fat diets (HFDs) induce hepatic insulin resistance in mice through CB1R-mediated inhibition of insulin signaling and clearance." (PMID 31035653, 2019). "In this integrative analysis, insulin resistance, insulin, and MAPK signaling pathways were overrepresented in high and low fatty acid groups." (PMID 31354792, 2019). "Altogether, these data indicate that GT supplementation protects against systemic insulin resistance (IR) improving hepatic insulin sensitivity." (PMID 31885789, 2019). "These reductions indicate a less damped response to insulin stimulation following the diet intervention, which is in line with previous studies reporting a reduction in whole body insulin resistance following prolonged caloric restriction." (PMID 31581241, 2019). "Participants in the mangosteen pericarp group showed significantly reduced insulin levels and demonstrated reduced insulin resistance." (PMID 30918489, 2019). "Clinically, evidence for involvement of insulin signaling pathways in DM1 is based on the increased incidence of insulin resistance seen in clinical practice and recent trial evidence of beneficial effects of metformin on muscle function." (PMID 31849810, 2019). "Defects in insulin action (insulin resistance) and insulin secretion (β cell dysfunction) are two key players in the pathophysiology of T2D." (PMID 32184858, 2019). "Taken together, these results suggested that blueberry can improve insulin sensitivity and glucose tolerance under HFD stress condition, and therefore delay insulin resistance caused by HFD feeding." (PMID 31139236, 2019). "The glucose tolerance test (GTT) and insulin tolerance test (ITT) showed that compound C alleviated insulin resistance." (PMID 31485221, 2019). "To investigate the effects of visfatin on insulin resistance, we evaluated insulin-signaling pathways, such as IR, IRS-1, GSK, and AKT using immunoblotting." (PMID 31396538, 2019). "ER stress significantly contributes to the development of insulin resistance by impairing insulin signaling through the activation of JNK, followed by phosphorylation of Ser307 in IRS1." (PMID 31246177, 2019). "After adjustment for age and BMI, there was a trend for positive associations between urinary CML levels and fasting (p = 0.06) and 2 h insulin (p = 0.05) levels, and insulin resistance measured by homeostatic model assessment (HOMA-IR) (p = 0.06)." (PMID 31295874, 2019). "Insulin resistance is typically defined as the reduced ability of insulin to induce glucose uptake by classic targets such as fat, liver, and skeletal muscle, leading to a common manifestation of obesity and a prelude to type 2 diabetes." (PMID 31013778, 2019). "In conclusion, treatment with CDCA, through orchestrating six players, was able to ameliorate insulin resistance and enhance insulin sensitivity to improve cognition and reduce neurodegeneration in AlCl3-treated rats." (PMID 31137621, 2019). "In particular, hepatic insulin resistance is correlated to a decrease in insulin signal transmission for inhibiting glucose production and insulin-stimulated hepatic lipogenesis." (PMID 31171927, 2019).
Insulin resistance (continued). "As insulin continues to stimulate hepatic fatty acid synthesis, even in an insulin-resistant state, insulin resistance and the resulting hyperinsulinemia increases de novo lipogenesis." (PMID 31075962, 2019). "HOMA-IR and QUICKI are commonly used as indicators of insulin resistance and β-cell function and of insulin sensitivity, respectively." (PMID 30841887, 2019). "Some researchers suggested that the serum ANGPTL8 level was significantly increased in type 2 diabetes patients; the ANGPTL8 level was positively correlated with insulin resistance and negatively correlated with insulin sensitivity." (PMID 31346314, 2019). "The basal HGP decreased significantly and the insulin secretion/insulin resistance (disposition) index increased significantly." (PMID 31470605, 2019). "Herein, we review the current knowledge that supports the impact of insulin signaling and other insulin resistance related signals as modulators of trained immunity." (PMID 31244863, 2019). "In conclusion, our findings demonstrate that SSE activates the insulin signaling cascade and highlight its potential as a novel botanical drug for the treatment of insulin resistance." (PMID 31234331, 2019). "Our analysis has revealed no relevant association between PFC and fasting glucose metabolism biomarkers (glucose, insulin, homeostatic model assessment for insulin resistance (HOMA-IR), HbA1c)." (PMID 31018616, 2019). "Impaired insulin activation of AKT reflects muscle insulin resistance and induces atrophy and apoptosis." (PMID 31455371, 2019). "Further on this, the role of inhibitory serine phosphorylation on IRS1 in the case of insulin resistance has been reported in most of the insulin target tissues including brain." (PMID 31143098, 2019). "They reported an inverse relationship between dietary anthocyanins and flavones and insulin resistance, fasting insulin and markers of inflammation in women 18–76 years old." (PMID 31013914, 2019). "HCV NS5A genotype 3a contributes to insulin resistance by interfering with the functional state of AKT/PKB of insulin signaling pathway." (PMID 30992506, 2019). "SUR1 is primarily responsible for insulin secretion and has potential influence in insulin resistance." (PMID 30616503, 2019). "Rosiglitazone, which is representative of thiazolidinediones drugs, can improve insulin resistance and stimulate insulin secretion." (PMID 30651718, 2019). "Insulin resistance in the skeletal muscles and in adipose tissue is followed initially by an increase in insulin production in pancreatic β-cells." (PMID 31222113, 2019). "Supplementing mouse diets with HON for 5 weeks significantly lowered blood HbA1c and plasma insulin levels, and improved glucose intolerance and insulin resistance compared to control db/db mice." (PMID 31075962, 2019). "Skeletal muscle is the primary site of insulin-induced glucose uptake and defects in skeletal-muscle metabolism contribute to insulin resistance." (PMID 31896238, 2019). "The NEFAs impair insulin signalling and lead to skeletal and hepatic insulin resistance, contributing to the pathophysiology of type 2 diabetes." (PMID 30729259, 2019). "Insulin resistance can result from various situations including abnormal insulin signaling, lipotoxicity, inflammation, mitochondrial dysfunction, and endoplasmic reticulum (ER) stress." (PMID 30717446, 2019). "HFD-fed p66Shc KO females showed increases of weight and plasma insulin levels resembling the insulin resistance phenotype observed in wild-type mice." (PMID 31641124, 2019). "By definition, EMS is related to insulin resistance (IR), insulin dysregulation and obesity, as well as hyperleptinemia and past or chronic laminitis." (PMID 30678275, 2019). "Specific metabolic side-effects such as glucose, insulin, homeostatic model assessment for insulin resistance, total cholesterol, LDL cholesterol, HDL cholesterol, and triglycerides will be addressed in future reviews." (PMID 31303314, 2019).
Insulin resistance (continued). "SIH is characterized by insulin resistance and an excess of the counterbalancing hormones of insulin, including glucagon, catecholamines, cortisol, and growth hormone." (PMID 30908518, 2019). "The levels of various anti-insulin hormones increased in fertile women and involved in promoting insulin resistance and the pathophysiology of arterial hypertension and angiogenesis." (PMID 31790364, 2019). "Overall, it appears that probiotic yogurt provided no significant improvement compared with the control in glycemic markers including HbA1c, fasting insulin and glucose, and insulin resistance measured by HOMA-IR." (PMID 30897796, 2019). "Genetic aspects play a role in insulin resistance in both adults and children by creating alterations in the pathways related to insulin metabolism." (PMID 30866603, 2019). "Previous studies showed that letrozole treatment of female mice resulted in increased FBG and insulin levels and insulin resistance." (PMID 31568518, 2019). "Insulin resistance leads to abnormalities in hepatic glucose output, and leads to hyperglycemia, which results in further worsening of the hepatic insulin insensitivity." (PMID 31215434, 2019). "It has many applications in obesity and insulin resistance research such as lipid synthesis, white vs. brown adipose tissue development, insulin-sensitizing drug action." (PMID 31731552, 2019). "Inflammation can directly contribute to insulin resistance by disrupting the insulin signaling pathway, in part via PTP1B activation." (PMID 31737637, 2019). "Studies have shown that NFE2 improves hepatic insulin sensitivity and whole-body insulin resistance." (PMID 31455213, 2019). "In our study, diabetic rats exhibited insulin resistance as confirmed by 137% increase of fasting serum insulin in the presence of moderate stable hyperglycemia." (PMID 30621352, 2019). "Endothelial insulin resistance is insulin‐insensitivity in the vascular endothelium and can be observed in experimental models." (PMID 30885039, 2019). "Oxidative stress can also contribute to insulin resistance by impairing insulin signal transduction." (PMID 31035653, 2019). "Flavonoid compounds have been reported to reduce whole-body adiposity, ameliorate metabolic lipid disorder, improve insulin sensitivity and benefit other disorders characterised by insulin resistance in high fat diet induced obesity mice." (PMID 31488120, 2019). "Insulin resistance is a deficit in signal transduction from insulin such as inactivation of PI3 kinase‐Akt signaling pathway." (PMID 31289664, 2019). "Next, we checked if the substantial reduction of hyperglycemia correlated with the improvement in insulin sensitivity in the treatment groups, approximated as reduced insulin resistance (HOMA-IR index)." (PMID 31167512, 2019). "Consistent with the very early manifestation of insulin resistance in CKD and with the cumulative nature of its deleterious effects, defected insulin signalling has been implicated in the aetiology of uraemic myopathy." (PMID 31195596, 2019). "HOMA insulin resistance index (HOMA-IR) highly correlates with the insulin sensitivity assessed by the euglycemic–hyperinsulinemic clamp in subjects with various degrees of glucose tolerance." (PMID 30934836, 2019). "Blueberry-supplemented diet can prevent obesity-induced insulin resistance by improving insulin sensitivity and protecting pancreatic β-cells." (PMID 31139236, 2019). "Patients with Glu 460 mutation had impaired insulin dissociation from INSR in endosomes, which led to impaired recycling and severe insulin resistance." (PMID 31658625, 2019). "Across worsening CKD stages, we noted increased concentrations of triacylglycerols (TAG), glucose, insulin, homeostatic model of insulin resistance (HOMA IR), C-reactive protein (CRP) and K+." (PMID 31109090, 2019).
Insulin resistance (continued). "mTOR causes the serine/threonine phosphorylation of IRS by activating S6K, and reduces its ability to be phosphorylated on tyrosine residues, which results in impaired insulin signaling and insulin resistance." (PMID 31824416, 2019). "A significant decrease was also observed in fasting insulin, homeostasis model assessment of insulin resistance." (PMID 34466504, 2019). "In obesity, there is impaired insulin signaling in peripheral tissues leading to insulin resistance." (PMID 31749085, 2019). "In accordance with the anti-obesity effect, BBR reduced serum lipids, glucose and insulin levels and ameliorated insulin resistance of the mice significantly (p < 0.05 or p < 0.01 vs. HFD group)." (PMID 31527742, 2019). "Intraperitoneal glucose and insulin tolerance tests demonstrated cabergoline to significantly improve glucose levels and to prevent insulin resistance." (PMID 31191454, 2019). "Otherwise, the concept that fat deposition in the liver also contributes to hepatic insulin resistance by the activation of enzymes that impair hepatic insulin signaling and by the altered adipokine secretion in subjects with NAFLD has been suggested." (PMID 31682638, 2019). "Insulin signaling plays an important role in β-cell function, survival, and compensation to peripheral insulin resistance." (PMID 31311313, 2019). "In states of obesity and insulin resistance, insulin levels typically increase to maintain normal glucose tolerance." (PMID 31139236, 2019). "Obesity-related insulin resistance (IR) is a dysmetabolic condition in which insulin target tissues (namely muscle, liver, and fat) fail to properly respond to insulin." (PMID 31394876, 2019). "Obesity induces brain insulin resistance, which blunts the suppressive action of insulin on food intake, thus inducing more severe obesity." (PMID 30875909, 2019). "An impaired biological response to insulin in the brain, known as central insulin resistance, was identified during stroke and traumatic brain injury, for which glutamate excitotoxicity is a common pathogenic factor." (PMID 31856878, 2019). "Type 2 diabetes is characterized by insulin resistance, reduced insulin sensitivity, and impaired pancreatic β-cell function." (PMID 32010641, 2019). "There was a correlation between insulin (p-value = 0.043), Homeostatic Model Assessment for Insulin Resistance (HOMA-IR)(p-value = 0.045) and apelin gene expression in visceral adipose tissue." (PMID 31548844, 2019). "Increased insulin levels can indicate insulin resistance, as hyperinsulinemia is a common symptom in T2D patients." (PMID 30768595, 2019). "Individuals in the current study were overweight or obese and had elevated fasting insulin concentrations with insulin resistance." (PMID 31035472, 2019). "Hyperinsulinemia and insulin resistance in the periphery can produce hypoinsulinemia and/or modified/dampened insulin signaling in the brain." (PMID 31035472, 2019). "Fasting blood glucose and insulin levels were used to calculate the homeostatic model assessment of insulin resistance (HOMA-IR)." (PMID 30249943, 2019). "Systemic infusion of GLP-1 improves muscle insulin action by potently recruiting muscle microvasculature in rats with either acute (lipid infusion) or chronic (high-fat diet (HFD) feeding) insulin resistance." (PMID 30699907, 2019). "As with other DM1 phenotypes, insulin signaling abnormalities, such as insulin resistance, occur only in a subset of DM1 patients." (PMID 31849810, 2019). "HOMA-IR is a criterion for assessing β-cell function and insulin resistance from basal (fasting) glucose and insulin or C-peptide concentrations." (PMID 30763324, 2019). "Fasting plasma glucose, insulin, insulin resistance (HOMA-IR index, IRI), the S-100β protein level, and the inflammatory mediators IL-1β, IL-6 and TNF-α were assessed after surgery (postoperative day (POD) 1 and 3)." (PMID 31092210, 2019).
Insulin resistance (continued). "Despite promoting growth, prolonged exposure to high insulin concentrations in this cell line has shown to induce insulin resistance." (PMID 31635074, 2019). "As marker for insulin resistance, calculated whole-body insulin sensitivity was used and was found to be lower in patients without an increase of asprosin during hypoglycemia." (PMID 31536600, 2019). "Several pathways emerged repeatedly, and the most commonly represented pathways included focal adhesion (15 miRNAs), regulation of actin cytoskeleton, insulin signaling, insulin resistance, MAPK signaling, and ErbB signaling." (PMID 30973878, 2019). "Continuous overnutrition with insulin resistance impairs insulin secretion by pancreatic β-cells, which eventually leads to overt T2D." (PMID 31798464, 2019). "There were no changes in body weight, blood pressure, lipid profile, fasting glucose and insulin, and homeostatic model assessment of insulin resistance (HOMA-IR)." (PMID 31412242, 2019). "Obesity is strongly linked to insulin resistance and excess plasma free-fatty acids (FFA) have been established to impair the ability of insulin to suppress hepatic glucose output and to stimulate glucose uptake by skeletal muscle." (PMID 30871083, 2019). "After 10 weeks, mice that continued on the high-fat diet showed significant increases in body weight, blood glucose, insulin, and leptin levels and exhibited impaired oral glucose tolerance, insulin resistance, and pancreatic β-cell dysfunction." (PMID 31382619, 2019). "T2DM involves multiple disorders, including of lipid and glucose metabolism, β-cell dysfunction, chronic low-grade inflammation, and oxidative stress, which result in insulin resistance and insufficient insulin secretion." (PMID 31293553, 2019). "Future studies are needed to investigate if E4orf1-induced reduction in endogenous insulin response will help reduce pancreatic β cell damage that often follows insulin resistance." (PMID 31127081, 2019). "In an in vitro human hyperinsulinemia-induced insulin resistance model, activation of LXRs restores insulin sensitivity and decreases inflammatory phenotype." (PMID 31708874, 2019). "Many factors play important roles in the development of glucose intolerance in individuals with type 2 diabetes (T2D), such as impaired insulin secretion and insulin resistance." (PMID 31690291, 2019). "Materials and Methods: Twenty-four obese subjects were investigated for body mass index (BMI), total fasting BA, insulin, homeostasis model assessment of insulin resistance (HOMA-IR), and leptin before and at 7 and 30 d after SG." (PMID 31766784, 2019). "The insulin secretion begins to increase during the early insulin resistance development through β-cell compensation, such that FPG level is maintained at the normal level." (PMID 31491867, 2019). "The key findings from this study revealed that the inactivation of the NF-κB pathway and silencing of SAA1 exert a positive effect on insulin resistance through the enhancement of insulin sensitivity both in vitro and in vivo." (PMID 31060494, 2019). "Changes in glucose and insulin concentrations served to calculate changes in insulin resistance using the HOMA-IR procedure." (PMID 31261978, 2019). "The insulin, insulin resistance index, and ba‐PWV levels were significantly higher in T2DM patients than in HCs (P < .05), which is consistent with our diagnosis in the inpatient clinic." (PMID 34553107, 2019). "Type 2 diabetes (T2D) is the most common type of diabetes and is a consequence of both downregulated insulin secretion and increased insulin resistance." (PMID 31896238, 2019). "The contribution of disturbed NEFA metabolism to the development of insulin resistance highlights the need to include adipose tissue NEFA metabolism when investigating disturbances in the glucose-insulin regulatory system during disease development." (PMID 31581241, 2019).